TNF (tumor necrosis factor)
Diseases named in the same sentence as TNF in open-access papers (continued):
Sharing a sentence is not in itself a finding about the gene and the disease.
COVID-19 (continued). "The levels of cytokines including IL-8 and TNF-α, which contribute to the aggravation of COVID-19 infection and represent the morbidity of COVID-19 patients, are associated with chronic cough." (PMID 36611603, 2023). "IL-8 has been suggested as a target for anti-cancer drugs and has been associated with adverse outcomes in COVID-19 patients, along with TNF-α, IL-6, IL-1β, and IL-33." (PMID 37627815, 2023). "Inflammatory mediators primarily associated with the cytokine storm in COVID-19 patients such as TNF-α, IL-1β, IL-6, IL-8, VEGF, and GM-SCF were elevated in both apical and basal media." (PMID 37200377, 2023). "Severe COVID-19 is closely associated with cytokine storms caused by proinflammatory cytokines, such as TNF-α." (PMID 37047115, 2023). "Probiotics also have an immunomodulating role in the cytokine storm (IL-1B, IL-6, IL-15, IL-15, IL-17 IFN-g, TNF-a), and it can thus be deduced that probiotics are involved in fighting the cytokine storm associated with COVID-19." (PMID 37049576, 2023). "Critical and fatal COVID-19 outcomes in adults have been associated with elevated levels of mostly IL-6, IL-1β, and TNF-α, along with a reduced and delayed production of type I IFNs." (PMID 37047752, 2023). "Recent studies have shown that serum levels of TNF-α have increased significantly in patients with COVID-19, and there is a positive and significant association between elevated serum TNF-α levels and disease severity." (PMID 37654571, 2023). "Cytokines (IL-2R, IL-6, IL-8, TNF-α, and IL-10) were significantly associated with in-hospital mortality in COVID-19 patients." (PMID 37735372, 2023). "Compared to other viral diseases such as influenza, COVID-19 generally has higher TNFα/IL-1β-associated inflammation and lower interferon responses." (PMID 37090709, 2023). "Further molecular docking revealed that quercetin has a higher affinity for IL6 and IL10 in the TNF signaling pathway associated with COVID-19." (PMID 38050310, 2023). "The elevations of IL-10, IL-23, and TNF-α levels were seen in severe and critical cases of COVID-19 patients and their elevations were linked to the in-hospital mortality of the disease." (PMID 37283736, 2023). "The original levels of five cytokines were statistically significantly associated with COVID-19 mortality, i.e., IL-6 (p < 0.001), IL-2R (p < 0.001), IL-8 (p < 0.001), IL-10 (p < 0.001), and TNF-α (p < 0.05)." (PMID 37735372, 2023). "The increase in pro-inflammatory cytokines, including IL-6, IFN-γ, and TNF-α, has been proven in patients with COVID-19 and found to be associated with COVID-19 disease severity, and thus, some patients have responded to IL-6 blockade." (PMID 37602239, 2023). "Pro-inflammatory cytokines, in particular elevated levels of C-reactive protein (CRP), D-dimer, and interleukin (IL) 1β, IL6, IL8, IL17, and tumor necrosis factor α (TNF-α), are associated with the worst outcome and high mortality in COVID-19 patients." (PMID 37534078, 2023). "IL-1, another key proinflammatory cytokine, had the best correlation with COVID-19-associated thrombotic events compared to IL-6 and TNF-α in one study." (PMID 36979908, 2023). "As a result, the overproduction of proinflammatory cytokines during a cytokine storm seen in COVID-19 patients is unequivocally associated with the activation of the TNF-α signaling pathway." (PMID 37047115, 2023). "COVID-19-positive patients have a high profile of interleukins (IL-6, IL-10, etc.)and tumor necrosis factor-alpha (TNF-α), causing a cytokine storm and suppression of GSH." (PMID 38235136, 2023). "Pulmonary edema, acute respiratory distress syndrome, and ventilatory dysfunction caused by COVID-19 are caused by the acute release of inflammatory cytokines IL-2, IL-6, IL-7, and TNF-α." (PMID 37175774, 2023). "In path c, SB203580 can affect p38, while abnormalities in p38, IL-6, and tumor necrosis factor-α (TNFα) have all been shown to be associated with COVID-19." (PMID 37632414, 2023).
COVID-19 (continued). "Cytokines such as IL-6 and TNF-α, found in the serum of severe COVID-19 patients, cause decreased ATP production and abnormal generation of mtROS." (PMID 37869674, 2023). "Increased TNF-α has been observed in COVID-19 vaccine-associated myocarditis, indicating that there is risk for fibrosis even if patients appear to recover fully." (PMID 36851240, 2023). "NKG2A expression along with decreased IFN-γ, granzyme B, and TNF-α production is associated with NK cell exhaustion and disease progression in COVID-19 patients." (PMID 36793739, 2023). "Recent reports demonstrate that IL-6 and TNF-α were overexpressed in COVID-19 patients, causing inflammation." (PMID 36817449, 2023). "Down-regulation of SIRT 1 in COVID-19 is associated and highly correlated with elevated levels of IL-1β, IL-6, IL-8, and TNF-α." (PMID 37486805, 2023). "For example, glucocorticoids have been associated with worse COVID-19 outcomes, whereas anti-TNF therapies appear to reduce the risk of hospitalization." (PMID 38239614, 2023). "Mitochondrial ROS mediate various signaling pathways, increase the expression of inflammatory cytokines (IL-6, IL-1β, TNF-α, etc.), and increase the risk of thrombosis in patients with COVID-19." (PMID 37834324, 2023). "Upon activation, neutrophils and monocytes copiously release various inflammatory cytokines, including IL-8, TNF-α, and, most notably, IL-6, which has been associated as an indicator of mortality among severe COVID-19 patients." (PMID 36634048, 2023). "Due to the association of uncontrolled inflammation with severe COVID-19 and unfavorable outcomes, we investigated IL-6, IL-1β, and TNF as inflammatory markers in the respiratory track." (PMID 37752151, 2023). "Serum levels of IL-1β, IL-6, IL-8, and TNF-α are elevated in COVID-19 patients and are associated with severe infection." (PMID 37376569, 2023). "Elevated levels of plasma IL-1β, IL-6, and TNF were shown to be associated with postacute sequelae of COVID-19." (PMID 37228441, 2023). "It has been shown that severe COVID-19 is associated with a significant derangement in proinflammatory cytokines, namely, IL-1β, IL-2, IL-6, IL-8, or TNF-α, often referred to as the “cytokine storm”." (PMID 37762549, 2023). "Regarding TNF-α, it has been well established that it is a risk factor for death in COVID-19 patients with severe or critical disease." (PMID 37283736, 2023). "Tumor necrosis factor alpha, a pro-inflammatory cytokine, is elevated both in acute COVID-19 and acute sepsis and is linked to more severe disease and worse prognosis." (PMID 36844209, 2023). "First, the probability that TNF-associated SNPs impact severe COVID-19 outcomes via causal pathways apart from TNF levels cannot be completely excluded." (PMID 37397483, 2023). "The overexpression of TNF-α has been reported as an independent risk factor of death among COVID-19 patients with critical conditions." (PMID 37047115, 2023). "Hyperferritinemia has been linked to ferroptosis and organ damage as a result of TNF-antagonist use, making COVID-19 patients more susceptible to fungal coinfections." (PMID 37072718, 2023). "A few genes, as NFKBIA, ICAM1, CXCL8, and TNFAIP3 are involved in NF-κB signaling and TNF signaling pathways, which have been known to cause inflammation and cytokine storms, augmenting COVID-19 severity." (PMID 37701571, 2023). "Several studies have consistently shown that increased TNFα serum levels on hospital admission are associated with the risk of mortality in COVID-19 patients." (PMID 36829885, 2023). "Because COVID-19 causes a cytokine storm by increasing pro-inflammatory cytokines such as TNF-α, IL-6, and IL-1β, we also analyzed these cytokine levels in the media of cells treated without or with the RBD for 24–120 h." (PMID 36982738, 2023).
COVID-19 (continued). "One of the most comprehensive studies to date assessed plasma levels of these four cytokines in 1,484 hospitalised patients with COVID-19 and found robust associations between IL-6, IL-8 and TNFα levels and mortality – a finding widely replicated." (PMID 37063871, 2023). "High levels of TNF in COVID-19 patients' plasma and tissues are associated with poor prognosis and early mortality." (PMID 37163438, 2023). "Considering the profound immunomodulatory roles of TNF-α, it can potentially serve as a diagnostic or prognostic marker for severe COVID-19 and as a molecular target for TNF-α inhibitors in COVID-19 treatment and management." (PMID 37047115, 2023). "Evidently, thiopurine monotherapy and the combination thiopurines with TNF antagonists are associated with significantly increased risk of severe COVID-19 compared with TNF monotherapy." (PMID 35223745, 2022). "Our findings showed decreased levels of Inhibin B, but not testosterone, to be significantly and inversely linked to TNF-α levels in both age subgroups of COVID-19 patients." (PMID 36381078, 2022). "One study described similar results in patients with COVID-19 and found an inverse association between serum TNF-α levels and T-cell counts." (PMID 36363785, 2022). "No definitive results were drawn regarding the association between TNF-α and vitamin D and COVID-19 severity and mortality." (PMID 35215138, 2022). "Specifically, rs1799964 in the promoter of inflammation-related gene TNF was found to be associated with COVID-19 severity." (PMID 36531218, 2022). "Recent research suggested that the inflammation cascade in severe COVID-19 patients with respiratory failure are intricately associated with an increase in TNF-α, IL-6 and MCP-1." (PMID 36135185, 2022). "Another report also suggested that the magnitude of cytokine secretion is associated with severity of COVID-19 and that postmortem lung samples showed higher endothelial expression of IL-6 and TNF-α in the diseased condition than in control condition." (PMID 34463916, 2022). "The results of the meta-analysis were that each increase in the TNF-α level of 1 pg/mL significantly increased the risk of developing severe COVID-19 (crude OR = 1.1004; 95% CI 1.0185–1.1890; p = 0.02)." (PMID 35215138, 2022). "GI symptoms in COVID-19 have also been associated with elevated liver enzymes while increased markers of inflammation such as TNFα and IL-6 have separately been associated with severe and/or fatal disease." (PMID 36032119, 2022). "Initial diminished IFN-I responses and enhanced IL-6 and tumor necrosis factor (TNF) responses were reported to be associated with the development of severe acute COVID-19." (PMID 36430870, 2022). "Increased pro-inflammatory cytokine levels of IL6 and TNFα can also cause lymphocytopenia in severe COVID-19 patients." (PMID 35784278, 2022). "The meta-analysis showed that each increase in the TNF-α level of 1 pg/mL insignificantly increased the risk of developing severe COVID-19 (aOR = 1.0304; 95% CI 0.8178–1.2983; p = 0.80)." (PMID 35215138, 2022). "Cytokine storm is characterized by increased levels of cytokines including tumor necrosis factor-alpha (TNF-α), interleukin (IL)-6, etc. in the plasma and is associated with worsening of the COVID-19 patient’s clinical condition." (PMID 36457636, 2022). "Higher IL-17 levels in nasopharyngeal swabs and lung autopsies of COVID-19 patients were associated with higher levels of proinflammatory cytokines, including IL-1β, TNFα, IL-6, IL-8, and IL-23." (PMID 36136963, 2022). "The oversecretion of proinflammatory cytokines such as IL-6, IL-8, and TNF-α during COVID-19 causes pulmonary dysfunction, which exacerbates clinical symptoms and is improved by suppressing the immune system." (PMID 36531832, 2022). "Association studies of TNF-α rs1800629 gene with COVID-19 prognosis or susceptibility included in the systematic review." (PMID 35432458, 2022).
COVID-19 (continued). "A possible reason is that these patients have routinely received anti-TNF-α treatment, and anti-TNF-α antibody is associated with lower hospitalization and less-severe COVID-19." (PMID 36297092, 2022). "Overall, high levels of TNF-α, IL-6, IL-8, and IL-10 have been associated with disease severity and poor survival from COVID-19." (PMID 34987205, 2022). "It is currently acknowledged that severe forms of COVID-19 are associated with the release of cytokines, such as IL-2, IL-6, IL-7, IL-10, tumor necrosis factor (TNF), and granulocyte colony-stimulating factor (GCSF)." (PMID 35743583, 2022). "Immune dysregulation, a hallmark of COVID-19 course and severity, is mainly orchestrated by cytokines and chemokines (e.g., IL-6, IL-1β, IL-8, IL-18, TNF-a) that are identified as tumorigenesis drivers." (PMID 36298472, 2022). "GWAS-based pathway enrichment analysis revealed that 19 biological pathways, including cytokine-cytokine receptor interaction, influenza A, and TNF signaling, were significantly associated with hospitalization in COVID-19 patients." (PMID 35172892, 2022). "Together with other clinical changes, increased oxidative stress and proinflammatory cytokines (IFN-γ and TNF-α) can plausibly be implicated in immune balance shifts towards a decrease in COVID-19-specific antibodies." (PMID 36354670, 2022). "In particular, we showed the activation of human dendritic cells (DC) and monocytes, demonstrating that these cells produced high levels of IL-6 and TNF-α –two hallmark cytokines in COVID-19-associated CRS." (PMID 35392091, 2022). "Growing research data suggests that the severity of COVID-19 is linked with higher levels of inflammatory mediators, such as cytokines, chemokines, tumor necrosis factor, C-reactive protein, ferritin, and D-dimers." (PMID 36431254, 2022). "First, ectopic fat exacerbates the inflammation caused by COVID-19 by the upregulation of proinflammatory cytokines like interleukin-6 (IL-6) and tumor necrosis factor-alpha (TNF-α), angiotensin II (ATII), and prothrombotics." (PMID 35721716, 2022). "An increase in TNF-α levels in the peripheral blood of the respiratory tract is associated with patients with severe COVID-19." (PMID 35891437, 2022). "Among other cytokines and inflammatory mediators, IL-1, -6, TNF-α and histamine have been strongly linked to COVID-19 severity and associated mortality." (PMID 35305615, 2022). "After the neutrophils and monocytes/macrophages migrate to the site of infection, the increased level of pro-inflammatory cytokines (IL-6, IL-8, IL-12, TNF-α, etc.) causes the immunopathology of COVID-19 in the lungs, i.e., the cytokine storm." (PMID 36423150, 2022). "Plasma proinflammatory cytokines, including IL-6 and tumor necrosis factor (TNF), and several chemokines, have been detected at elevated concentration in patients with COVID-19 and were associated with disease severity." (PMID 36439166, 2022). "The elevation of IL-6 and TNF-α was shown to be associated with the severity of COVID-19 due to the cytokine storms, and remarkable elevation of plasma LGALS3BP was also observed in COVID-19 ICU patients." (PMID 35958562, 2022). "While it is proposed that the risk of COVID-19-related hospital admission increases by using rituximab, it decreases in patients under anti-tumor necrosis factor (anti-TNF) agents." (PMID 35456195, 2022). "Though other cytokines and chemokines must be involved, these results underline the therapeutic potential of IFNγ and TNF blockade as COVID-19 treatment." (PMID 35023830, 2022). "Further, two other large worldwide registries of individuals with immune-mediated inflammatory diseases have demonstrated an inverse association of anti-TNF-alpha use and the severity of COVID-19-related outcomes." (PMID 36060521, 2022).
COVID-19 (continued). "Among TNFα or IL-1β saliva levels, higher IL-17 level in saliva of COVID-19 patients was associated with disease severity and worse clinical outcomes, defined as need for mechanical ventilation and/or death within 29 days of admission." (PMID 36136963, 2022). "For instance, methotrexate treatment significantly modulated pathways of chemokine signaling, cytokine-cytokine receptor interaction, TNF signaling, IL-17 signaling and Toll-like receptor signaling pathways associated with COVID-19 immunology." (PMID 36618412, 2022). "These large-scale data revealed that the serum levels of IL-6, IL-10, IL-2R, TNF-α, IL-1β, IL-4, IL-8, and IL-17 are potential risk factors for severity and high mortality in COVID-19." (PMID 35237162, 2022). "Serum cytokine levels that are elevated in patients with COVID-19-associated cytokine storm include TNF-α and IFN-γ." (PMID 36494757, 2022). "The use of TNF-inhibitors has been associated with a reduced risk of severe COVID-19 and augmented cellular vaccine responses." (PMID 35743605, 2022). "A study is reported that an exacerbated inflammatory response in severe COVID-19 patients associated with increased TNF-a and IL-6 potentially driven by NF-κB." (PMID 35223745, 2022). "Collectively, the combined immune response of IFN-γ and TNF-α was a hallmark of COVID-19 severity in CHIP (+) individuals." (PMID 36229591, 2022). "There were nine studies that analyzed the association between TNF-α and the severity and mortality of COVID-19." (PMID 35215138, 2022). "The cytokine storm in COVID-19 is caused by the interaction of multiple immunological components, including interleukins, chemokines, TNF-α, and IFNs." (PMID 36111104, 2022). "Many of the pro-inflammatory cytokines upregulated in COVID-19, such as tumor necrosis factor-α and interleukin-1, can cause lowering of erythropoietin production." (PMID 36297178, 2022). "A viral infection causes mortality in some severe COVID-19 cases and elevations in cytokines and acute phase reactants such as interleukin IL-6, tumor necrosis factor-a (TNFa), and ferritin." (PMID 36072227, 2022). "On the other hand, azathioprine, especially in combination with anti-TNF biological therapy, seems to be associated with increased risk of severe COVID-19." (PMID 36054100, 2022). "Numerous scientific articles have reported on the association of IL-6 and TNF-α with the severity and mortality of COVID-19." (PMID 36359509, 2022). "For example, variants in cytokine genes and tumor necrosis factor (TNF) affect COVID-19 susceptibility, severity, and complications." (PMID 35889989, 2022). "Three studies analyzed the association between the TNF-α level and COVID-19 mortality; these reported an HR value from a Cox regression analysis with the TNF-α level as a continuous variable." (PMID 35215138, 2022). "Next, we have assessed the association between IL-17, TNFα and IL-1β levels in saliva of severe COVID-19 cases with the survival outcomes of these patients." (PMID 36136963, 2022). "Biomarkers such as C-reactive protein (CRP), interleukin (IL)-8, interleukin-10 (IL-10) and tumor necrosis factor (TNF)-α are all considered as diagnostic biomarkers for COVID-19 patients in clinic." (PMID 36343035, 2022). "The relationship between elevated PCT and COVID-19 severity can be explained by the associated systemic inflammation and the release of the proinflammatory cytokines such as IL-6, IL-1β, and TNF-α, with subsequent induction of PCT synthesis." (PMID 36295550, 2022). "Levels of Eotaxin-3, MIP-1α, IL-12p70, TNF-α, IL-7, GM-CSF, and IL-23p40 were also significantly associated with monocyte-derived cfDNA in SOTRs with COVID-19 (p<0.05 and FDR<0.25)." (PMID 35075453, 2022). "This intracellular sensor is enabled by oxidized LDL and TNF α, causing activation and release of cytokines in patients with metabolic dysfunction, resulting in cardiovascular complications in COVID-19 patients." (PMID 35865966, 2022).